CRP (C-reactive protein)
Diseases named in the same sentence as CRP in open-access papers (continued):
Sharing a sentence is not in itself a finding about the gene and the disease.
chronic kidney disease (continued). "The RESCUE trial was a phase 2 trial that enrolled 264 patients with moderate to severe chronic kidney disease and high-sensitivity CRP of at least 2 mg/L." (PMID 37092016, 2023). "In a report of 158 patients with chronic kidney disease, red blood cell distribution width correlated with CRP, central diastolic blood pressure, and albuminuria." (PMID 37511843, 2023). "One study of chronic kidney disease revealed higher systemic inflammatory marker levels, such as C-reactive protein (CRP), interleukin (IL)-6, and tumor necrosis factor-α, in patients with low GNRI scores than those with high GNRI scores." (PMID 37799767, 2023). "Chronic heart disease and chronic kidney disease are two other common chronic diseases; CRP is an essential biomarker of both diseases." (PMID 35214519, 2022). "First, the serum concentration of CRP can be influenced by other factors, such as medications, smoking, alcohol consumption, chronic kidney disease, and other comorbidities." (PMID 36185864, 2022). "The results of the univariate analysis indicated that eruptive calcified nodules, chronic kidney disease, age, high-sensitivity C-reactive protein, maximal calcification arc, thrombus, and layered plaque were significantly associated with MACE." (PMID 35887782, 2022). "Chronic kidney disease (CKD) is associated with low-grade inflammation and increases the serum concentration of inflammatory markers, such as C-reactive protein, cytokines, TNF α, and adhesion molecules." (PMID 36012158, 2022). "This study aimed to determine C-reactive protein serum concentrations in stage IV chronic kidney disease dogs treated with intermittent hemodialysis." (PMID 36137129, 2022). "In a Swedish cohort of males with chronic kidney disease (n = 418), each unit increase in the PDI was associated with significantly decreased CRP and IL-6 concentrations." (PMID 36558530, 2022). "In chronic kidney disease dogs, the inflammatory process increases C-reactive protein concentrations." (PMID 36137129, 2022). "infantum antibody titres, globulins, gamma globulins, and C-reactive protein (CRP) in leishmaniotic dogs affected by chronic kidney disease (CKD)." (PMID 36316751, 2022). "The p66Shc hypomethylation increased significantly with MDA and CRP levels in subjects with chronic renal failure." (PMID 34529688, 2021). "Chronic kidney disease (OR = 14), C-reactive protein >100 IU/L (OR 6.964), and S. albumin <3 gm/dl (OR = 8) were detected to be risk factors for mortality in patients." (PMID 34285680, 2021). "In contrast, DMPs associated with C-reactive protein (CRP) levels were enriched for sites characteristic of granulocytes, and DMPs associated with chronic kidney disease were enriched for sites characteristic of monocytes." (PMID 33739972, 2021). "Logistic regression analysis indicated that chronic kidney disease (OR = 14.0), CRP >100 IU/L (OR = 6.964), and S. albumin <3 gm/dl (OR = 8.0) were risk factors associated with mortality and can guide in risk stratification." (PMID 34285680, 2021). "Regarding chronic kidney disease and periodontal treatment, an observational study on hemodialysis patients reported that periodontal treatment significantly improved blood CRP levels." (PMID 34262126, 2021). "Male sex, chronic kidney disease, desaturation, dyspnoea as well as lymphocytes count, CRP and serum creatinine at admission were included in a multivariate binary logistic regression model to identify associated factors of death." (PMID 33838684, 2021). "Ziltivekimab has earlier completed two early-stage trials in chronic kidney disease patients in which its administration reduced the levels of C-reactive protein (CRP)." (PMID 34829992, 2021). "Our patients with eGFR 30–60 at the time of contrast-enhanced CT had higher CRP levels and a higher incidence of chronic renal disease compared to patients with eGFR> 60 at the time of contrast-enhanced CT." (PMID 34465289, 2021).
chronic kidney disease (continued). "Another meta-analysis conducted on patients with chronic kidney disease indicated that bacterial therapy has significant beneficial effects on serum levels of C-reactive protein (CRP), total GSH, MDA, and total AO capacity." (PMID 34680457, 2021). "A similar attempt has been made to dynamically assess chronic kidney disease using C-reactive protein to get a time curve." (PMID 33568099, 2021). "Increased serum or plasma concentrations of inflammatory markers, including CRP, interleukin 6 and TNFα are consistently reported in patients with chronic kidney disease." (PMID 34827620, 2021). "Patient 3 was affected by chronic coronary artery disease, dilated cardiomyopathy, and chronic kidney disease; when TdP occurred, he was taking amiodarone, and CRP was elevated due to acute urinary infection." (PMID 32477142, 2020). "At univariate analysis, LDH, C Reactive Protein, procalcitonin, creatinin, Chronic Kidney Disease Epidemiology Collaboration, AST, white blood cells, LUSS, body temperature were all significantly associated with RT-PCT test outcomes." (PMID 33432268, 2020). "In humans, decreased levels of Prevotella copri and Faecalibacterium prausnitzii populations were observed in severe forms of chronic kidney disease (CKD), which also negatively correlate with the presence of important diagnostic markers, such as C-reactive protein and cystatin C levels." (PMID 32260384, 2020). "Chronic kidney disease involves chronic inflammation that is exemplified by the presence of increased levels of inflammatory markers such as C-reactive protein (CRP), IL-6, and TNF-α in the circulation." (PMID 30832377, 2019). "The constant conclusions were also drawn by subsequent investigations showing CRP as a significant predictor in patients with CKD/ end-stage renal disease." (PMID 31731708, 2019). "Adults with GA and neovascular AMD were older (P < 0.0001) and had higher serum CRP concentrations (P = 0.01) and chronic kidney disease (P = 0.01) compared with controls." (PMID 30621701, 2019). "The increased levels of CRP in this study population indicate the inflammatory response that usually occurs with chronic kidney disease." (PMID 29902980, 2018). "(CKD chronic kidney disease; hs-CRP: serum high-sensitive C-reactive protein; MVF: maximal voluntary force; nPCR: normalised protein catabolism rate)." (PMID 30067754, 2018). "The CRP-Chip was validated for detecting CRP in blood samples from chronic kidney disease patients and healthy subjects." (PMID 28346363, 2017). "Glycine is also negatively correlated with inflammatory markers like C-reactive protein in chronic kidney disease but in COPD patients, it is positively correlated." (PMID 29391845, 2017). "Numerous studies have reported an association between markers of inflammation like CRP, IL-6, TNF-α and fibrinogen and chronic kidney disease (CKD)." (PMID 28494192, 2017). "C-reactive protein (CRP), an acute phase reactant, is associated with all-cause mortality in patients with end-stage renal disease (ESRD)." (PMID 27212945, 2016). "In a multivariate regression analysis advanced age, DM, acute hyperglycemia (AHG), CRP and chronic kidney disease (CKD) were independent predictors of elevated GDF-15 levels (P < 0.05)." (PMID 27056183, 2016). "Recent studies showed an inverse relation of C-reactive protein (CRP) and renal function in chronic kidney disease and diabetic patients, respectively." (PMID 25259714, 2014). "High-intensity strength training also reduced interleukin (IL)-18, a pro-inflammatory cytokine, in HIV-infected patients and IL-6 and C-reactive protein (CRP) levels in older adults with chronic kidney disease compared to controls." (PMID 23855596, 2013). "In chronic kidney disease, plasma His concentrations are inversely correlated with CRP and hepatocyte growth factor, markers that reflect inflammation." (PMID 22303484, 2012).
chronic kidney disease (continued). "CRP gene polymorphisms are associated with serum C-reactive protein concentrations and may play a role in chronic kidney disease (CKD) progression." (PMID 21569369, 2011). "One proposed explanation for higher CRP concentrations with CKD is that there is diminished filtration of CRP in end-stage renal disease." (PMID 20078870, 2010). "Elevated CRP levels have been shown to correlate positively with the onset and progression of chronic kidney disease (CKD), suggesting that chronic inflammation may impair renal function by affecting tubular epithelial cells and glomeruli." (PMID 41227028, 2025). "Of six feature selection strategies compared, bootstrap inclusion frequency identified seven predictors: red blood cell count, preoperative C-reactive protein, chronic kidney disease, operative time, chronic obstructive pulmonary disease, body mass index, and blood transfusion." (PMID 40870423, 2025). "Recently, ziltivikimab, an IL‐6 inhibiting monoclonal antibody, has been tested in the RESCUE trial amongst participants with moderate to severe chronic kidney disease and an hs‐CRP levels of > 2.0 mg/L, where treatment for 12 weeks resulted in 77%–92% reduction in the median CRP levels." (PMID 40309624, 2025). "In chronic kidney disease, mitochondrial dysfunction, oxidative stress, immune dysfunction, and chronic low-grade inflammation are common, as reflected by elevated levels of circulating inflammatory markers, such as IL-1β, IL-6, and C-reactive protein." (PMID 40725180, 2025). "It has been reported that high levels of Eisenbergiella may contribute to chronic kidney disease, and experimental results have shown that Eisenbergiella is correlated with higher c-reactive protein levels." (PMID 39364150, 2024). "Hypomagnesemia plays a role in reducing leukocyte and macrophage activity, decreasing nitric oxide (NO) synthesis, increasing CRP and IL-1 levels, cytokine hypersecretion, and enhanced platelet aggregability—conditions that are further exacerbated in patients with chronic kidney disease (CKD)." (PMID 39796484, 2024). "The results showed that the CRP detection results of 41 urine samples from patients with chronic kidney disease (CKD) were highly consistent with the conventional homogeneous particle-enhanced turbidimetric immunoassay (PETIA) method’s detection results (R2 = 0.9910)." (PMID 38920587, 2024). "The ZEUS study is a phase 3 trial that is currently enrolling patients with chronic kidney disease and elevated high-sensitivity CRP to test whether ziltivekimab can reduce cardiovascular events." (PMID 37092016, 2023). "If we search for factors common to all types of catheters, we can define age, the level of inflammation (identified by correlations with CRP or procalcitonin), and renal function (identified by the presence of chronic kidney disease or serum creatinine levels) as common to both CVC and UC patients." (PMID 36292107, 2022). "As regards blood tests results, our study group was found with a significant increase in serum levels of inflammatory biomarkers, as WBCs, NLR, CRP, procalcitonin, with a mild chronic renal failure, and finally with a marked increase in serum levels of D-dimer and NT-proBNP." (PMID 36090992, 2022). "The multivariate linear regression model revealed that the independent predictors of longer hospitalisations included coexisting chronic kidney disease (parameter of regression = 0.914, p = 0.043) and a higher CRP concentration (parameter of regression = 0.013, p = 0.049)." (PMID 35627363, 2022). "Based on the values of C-reactive protein between groups, we observed an active inflammatory condition in patients with stages IV chronic renal failure submitted to intermittent hemodialysis as C-reactive protein concentrations were increased in the IHG when compared to CTG and CG." (PMID 36137129, 2022).
chronic kidney disease (continued). "One proposed explanation for this finding might be increased CRP values through diminished filtration in end-stage renal disease, as previously reported." (PMID 36139954, 2022). "The higher IDO activity and KT ratio in chronic kidney disease have also been linked with high-sensitive-CRP and soluble TNF receptor-I, regardless of age, body weight or serum creatinine." (PMID 35565678, 2022). "Chronic kidney disease and CRP at admission were independent factors of death." (PMID 33838684, 2021). "They found 5 independent pre-operative predictors of failure, including chronic kidney disease, liver cirrhosis, infection of a revision arthroplasty or arthroplasty for femoral neck fracture, cemented prosthesis, and presenting C-reactive protein > 11.5 mg/dL." (PMID 34118906, 2021). "Confusion with or without general symptoms is the most frequent initial presentation and was not a predictive factor of death while history of chronic kidney disease and CRP level at admission were significantly associated with mortality." (PMID 33838684, 2021). "The KDOQI Clinical Practice Guidelines for Nutrition in Chronic Renal Failure suggest that AGP may be more specific than CRP for detecting inflammation in MD patients." (PMID 34835927, 2021). "Moreover, PISA was shown to be related to increase of CRP in patients with end-stage renal diseases." (PMID 34134635, 2021). "Similarly, another meta‐analysis was conducted over the effects of CoQ10 supplementation on the metabolic profile including LDL, FBS, HDL, TG, HOMA‐IR, MDA, CRP, and creatinine in patients with chronic renal failure." (PMID 32328242, 2020). "Pairwise and network meta-analyses on the relationship between the efficacy of the use of statins with or without ezetimibe and reductions in low-density lipoprotein cholesterol (LDLc) and C-reactive protein (CRP) in patients with chronic kidney disease (CKD) are presented." (PMID 31222137, 2019). "Several other studies have also reported consistent results about the potential of inflammatory diet in inducing chronic kidney disease and reduced kidney function by increasing CRP concentrations, reducing glomerular filtration rate (GFR) and increase in BUN and creatinine." (PMID 30557399, 2018). "The following factors were significantly associated with in-hospital mortality in the unadjusted binary logistic regression analysis: SOFA score, acidosis, coagulopathy, episode of hypotension, blood lactate, albumin, creatinine, CRP value, and comorbidity with chronic kidney disease." (PMID 30423847, 2018). "Chronic kidney disease results in a state of chronic low-grade inflammation, with increases seen in pro-inflammatory markers such as interleukin 6 (IL-6) and C-reactive protein (CRP), which contributes to worsened mortality outcomes in this population." (PMID 28287463, 2017). "Myocardial injury, chronic kidney disease (CKD), and pulmonary infection are shown to be high risk factors for mortality of AHF patients, which were well characterized by troponin T (TNT), glomerular filtration rate (GFR), and C-reactive protein (CRP)." (PMID 27144175, 2016). "Thus, combined consumption of white wine and extra-virgin olive oil for two weeks decreased the plasma levels of CRP and IL-6 both in patients with chronic kidney disease and healthy individuals." (PMID 27077879, 2016). "Plasma levels of interleukin (IL)-1β, IL-1 receptor antagonist (IL-1RA), IL-6, tumor necrosis factor (TNF)-α, transforming growth factor (TGF)-β, high-sensitivity C-Reactive protein (hs-CRP), fibrinogen and serum albumin were measured in 3,939 Chronic Renal Insufficiency Cohort study participants." (PMID 25909952, 2015). "Baseline serum levels of anti-CRP-Ab seem to be a strong risk factor for a composite outcome of non-response, renal flare or end stage renal disease after two years of standard treatment of LN." (PMID 26704903, 2015).
chronic kidney disease (continued). "Furthermore, it has been shown that high sensitivity C-reactive protein (hs-CRP) is elevated in patients with chronic kidney disease (CKD)." (PMID 25051062, 2014). "Despite the positive attitude towards the use of surrogate endpoints among all stakeholders, they did not consider most currently used surrogates such as blood pressure, HbA1c, albuminuria and CRP valid substitutes for end-stage renal disease and cardiovascular (CV) outcomes." (PMID 25268242, 2014). "However, out of four proposed surrogates (blood pressure (BP), HbA1c, albuminuria, CRP) for cardiovascular outcomes or end-stage renal disease, only use of BP for cardiovascular outcomes was deemed moderately accurate (mean: 3.6, SD: 1.1)." (PMID 25268242, 2014). "An ADR risk score included age 65 years or more, female sex, conservatively managed end-stage renal disease, vascular disease, serum level of C-reactive protein more than 10 mg/L, serum level of albumin less than 3.5 g/dL, and the use of 8 medications or more during hospitalization." (PMID 24755778, 2014). "It is showed that CRP, a systematic inflammatory marker, could predict malnutrition in patients with end stage renal disease." (PMID 24349471, 2013). "High CRP has also been recognized as a prognostic indicator in chronic renal disease." (PMID 22292070, 2012). "Similarly, in another study, serum Hcy levels and C-reactive protein levels were significantly higher in patients with stage 3 chronic kidney disease (CKD) compared to those with stage 1 disorder." (PMID 19781090, 2009). "Even at initial stages of chronic renal failure, the CRP level is elevated." (PMID 19578522, 2008). "employed SHAP to identify serum cystatin C (SCysC) and serum creatinine (SCr) as the most critical indicators for classifying chronic kidney disease (CKD) stages, while factors such as blood pressure and CRP levels were less influential." (PMID 41403092, 2025). "The C-reactive protein/Lymphocyte Ratio (CLR) is a novel biomarker whose role in the development of chronic kidney disease (CKD) is not well understood." (PMID 39882264, 2024). "Chronic inflammation, reflected by an increased blood C-reactive protein (CRP) level, is common in patients with chronic kidney disease (CKD) and is involved in the development of renal anemia." (PMID 38311719, 2024). "Several traditional inflammatory cytokines, such as C-reactive protein (CRP), interleukin-6 (IL-6), and tumor necrosis factor-α (TNF-α), have been reported to aggravate kidney function impairment and increase the risk of death in patients with chronic kidney disease (CKD) and MHD." (PMID 37724554, 2023). "For GlycA and creatinine that had putative causal relationships with the FI, we performed additional subgroup analyses in the UKB to assess whether the associations could be driven by their associated traits, namely CRP and LDL‐cholesterol for GlycA, and chronic kidney disease for creatinine." (PMID 37184129, 2023). "Chronic kidney disease (CKD) associates an inflammatory process marked by inflammatory cytokines such as blood MCP-1 and IL-6 and C-reactive protein to albumin ratio in serum." (PMID 35735634, 2022). "His blood work was normal except for anion gap acidosis, lactic acidosis, acute kidney injury (AKI) on chronic kidney disease (CKD), elevated C-reactive protein (CRP), troponemia, and COVID polymerase chain reaction (PCR) positive." (PMID 35530896, 2022). "The laboratory tests revealed leukocytosis, anemia, 4 stage chronic kidney disease (CKD), and elevated total bilirubin (TB), CRP and N-terminal pro B-type natriuretic peptide (NT-pro-BNP)." (PMID 31952508, 2020). "CKD = chronic kidney disease; CRP = C-reactive protein; Hb = hemoglobin; IQR = interquartile range; n = number of patients; SD = standard deviation; TSAT = transferrin saturation; WHO = World Health Organization." (PMID 30614439, 2019).